IL13 (interleukin 13)
Diseases named in the same sentence as IL13 in open-access papers (continued):
Sharing a sentence is not in itself a finding about the gene and the disease.
chronic gastritis (4 papers, 2020 to 2024). Inflammation of the stomach that is chronic in nature. "Collectively, these findings suggest that IL-13 is generated by diverse subsets of immune cells during chronic gastritis, promoting changes in gastric epithelial cells associated with gastric cancer." (PMID 39193325, 2024). "For example, IL-33 contributes to host defense against parasitic and bacterial infections and exerts cardioprotective effects, however, in chronic gastritis, IL-33 release after parietal cell loss induces IL-13 production from ILC2s to promote intestinal goblet cell differentiation in mice." (PMID 39193325, 2024). "Specifically, the process is mediated by the activity of cytokines, such as IL-33 and IL-13, and cell types, such as mast cells, M2 macrophages, and eosinophils, which promote diffuse and chronic gastritis-dependent metaplasia." (PMID 38730659, 2024). "In particular, the activity of cytokines, such as IL-33 and IL-13, and cell types, such as mast cells, M2 macrophages and eosinophils, are intertwined in the process, promoting chronic gastritis-dependent and more diffuse metaplasia." (PMID 38339273, 2024). "Mice with AIG lacking the IL-13 receptor fail to exhibit neck cell expansion or metaplasia and anti-mouse IL-13-neutralizing antibodies inhibit and reverse disease progression during chronic gastritis." (PMID 39193325, 2024). "IL-13 expression has been observed increased in the gastric mucosa of TxA23 mice with AIG with a correlation with the level of metaplasia; neutralization of IL-13 using anti-mouse IL13 antibodies inhibits and reverses disease progression during chronic gastritis." (PMID 39193325, 2024). "Nonetheless, it has been reported that IL-33 induces IL-13 production from ILC2s to promote intestinal goblet cell differentiation within the colons of mice, indicating that the IL-33/IL-13 axis might play a relevant role in inducing intestinal metaplasia in the context of chronic gastritis." (PMID 38339273, 2024).
chronic lung disease (4 papers, 2019 to 2020). According to the definitions of the American and British Thoracic Societies, including pulmonary functional tests, X-rays, and CT scans for items such as fibrosis, bronchiectasis, bullae, emphysema, nodular or lymphomatous abnormalities. "For at least up to 6 months post WS/33 IAV infection, they specifically observed chronic lung disease that was associated with focal bronchiolization as well as mucus production and that was in part linked to IL-13." (PMID 33260910, 2020). "It is worthy of note that IL-13 is an important inducer of fibrosis in several chronic lung diseases, including IPF." (PMID 31581688, 2019).
colorectal tumour (4 papers, 2016 to 2026). "Prior investigations have linked ILC2‐derived IL‐13 secretion to the promotion of colorectal tumour progression via suppressive immune signalling." (PMID 41527493, 2026). "In conclusion, PGN has distinct biological effects on irradiated intestinal tissues and colorectal tumors via the IL13-Akt3-mTOR pathway." (PMID 27708223, 2016).
diabetic kidney disease (4 papers, 2019 to 2025). Progressive kidney disorder caused by vascular damage to the glomerular capillaries, in patients with diabetes mellitus. "In OVA/Alum model, IL-4 was also shown to increase in PTX3-treated mice, so was IL-13, though not significant, in line with the results observed in animal model of diabetic nephropathy." (PMID 32938460, 2020).
experimental autoimmune encephalomyelitis (4 papers, 2012 to 2026). An autoimmune demyelinating disease of the central nervous system that is produced experimentally in animals by the injection of homogenized brain or spinal cord in Freund's adjuvant. "Induction of a more tolerogenic gut DC phenotype and increases in IL-10 and IL-13 by manipulation of gut microbiota are associated with attenuation of subsequently induced experimental autoimmune encephalomyelitis." (PMID 24147013, 2013). "In experimental autoimmune encephalomyelitis (EAE), GA positively regulates inflammation by increasing anti-inflammatory IL-4, IL-10 and IL-13, while the pro-inflammatory cytokines IL-6, IL-12 and TNF-α are reduced." (PMID 36831209, 2023).
falciparum malaria (4 papers, 2012 to 2018). "A study done in a Thai population revealed that the SNP rs1881457, which is located in the same haplotype block in 5q31-33 region with the RAD50 gene and the promoter of IL13 is significantly associated with severe falciparum malaria." (PMID 22905743, 2012). "As such, the association between the IL-13 variants -7402 T/G (rs7719175) and -4729G/A (rs3091307) and susceptibility to SMA was determined in children (n = 387) presenting with clinical symptoms of falciparum malaria and resident in a holoendemic transmission region in western Kenya." (PMID 23521898, 2013). "Compared to control children (n = 106), children with moderately severe (n = 77) and severe falciparum malaria (n = 129) had significantly higher mononuclear cell arginase 1 mRNA, protein, and enzyme activity; lower NOS2 mRNA; lower plasma arginine; and higher plasma IL-10, IL-13, and IL-4." (PMID 27385484, 2016).
graft versus host disease (4 papers, 2014 to 2021). An immune system disorder that occurs after allogeneic hematopoietic stem cell transplant and is a reaction of donor immune cells against host tissues. "Using different cytokines, such as IL-6, IL-13, or LPS, it could generate BM-MDSCs in vitro and successfully treated diseases in vivo, like graft-versus-host disease, skin transplantation and pancreatic islet transplantation." (PMID 33250891, 2020). "This study also assessed gene expression profiling in skin of a sclerodermatous graft-versus-host disease (scl GVHD) model in Rag2–/– mice, which were found to also exhibit the IL-13 pathway activation resembling that in SSc patients of inflammatory subset." (PMID 26106387, 2015).
head and neck cancer (4 papers, 2013 to 2025). A primary or metastatic malignant neoplasm affecting the head and neck. "We have previously reported that IL-13Rα2, a receptor that binds IL-13 with high affinity, is uniquely overexpressed on some human head and neck cancers." (PMID 23421960, 2013). "In summary, our study demonstrates that our HNSCC mouse model is valuable for developing novel cancer therapeutic approaches, and that IL-13-PE has therapeutic potential to treat human head and neck cancer." (PMID 23421960, 2013). "IL-13-PE has been shown to have cytotoxic effects against head and neck cancer cell lines that are either positive for IL-13Rα2 or are stably transfected to express IL-13Rα2." (PMID 23421960, 2013). "Our study demonstrates that the Tgfbr1/Pten 2cKO mouse model of human HNSCC is a useful model for assessing antitumor activity of new cancer therapeutic agents, and that IL-13-PE has therapeutic potential to treat human head and neck cancer." (PMID 23421960, 2013). "Both transfectants acquired sensitivity to IL-13-PE confirming the relevance of the utility of IL-13-PE in head and neck cancer therapy." (PMID 23421960, 2013). "With the sensitivity of these HNSCC cell lines to IL-13-PE, we decided to test this immunotoxin treatment in a genetically engineered mouse model of head and neck cancer, the Tgfbr1/Pten 2cKO mice." (PMID 23421960, 2013).
Hepatitis (4 papers, 2017 to 2023). Inflammation of the liver. "Hepatitis is further aggravated, and HCC is further encouraged by the simultaneous production of TNF-α, IFN-γ, IL-12, IL-4, and IL-13." (PMID 36281288, 2022).
Hyperkeratosis (4 papers, 2022 to 2024). Hyperkeratosis is a histopathological term defining a thickened stratum corneum and may be present in many different skin conditions, with many possible overlaps. "IL-4/IL-13 treatment resulted in severe hyperkeratosis, spongiosis, and acanthosis in the RHE samples." (PMID 37047166, 2023). "This appears to be typical spongiosis and hyperkeratosis, in which IL-4/IL-13 cytokines suppress the maturation of desmosomes and weaken the binding of corneocytes." (PMID 35216228, 2022). "In this study, we show for the first time, that the addition of histamine to disease-associated full-thickness skin models stimulated with TH2 cytokines (IL-4, IL-13, IL-31) results in morphological changes of the epidermal layer, interpreted as hyperkeratosis." (PMID 36615633, 2023). "First, IL-4/IL-13-stimulated AD-HSE, like other in vitro AD-like models and AD patients, had altered epidermal morphology resembling spongiosis or hyperkeratosis." (PMID 35216228, 2022). "Compared with the control group, IL-4/IL-13 treatment yielded very thick EDL, even hyperkeratosis." (PMID 35216228, 2022).
leptospirosis (4 papers, 2012 to 2022). A contagious bacterial infection caused by spirochetes of the genus Leptospira. "The cytokine profile revealed that the levels of at least sixteen cytokines were significantly elevated in the leptospirosis patients’ sera, including the major proinflammatory factors IL-1β, IL-6 and TNF-α, and the major anti-inflammatory factors IL-4, IL-10 and IL-13." (PMID 22870312, 2012).
Listeria monocytogenes Infection (4 papers, 2011 to 2024). "Therefore, we demonstrate that mast cell TLR2 plays a crucial role in regulating the synthesis of IL-6 and IL-13 during Listeria monocytogenes infection in MC." (PMID 34194428, 2021). "In addition IL-13 is able to prime monocytes for IL-12 production, which is also observed in listeriosis." (PMID 21245915, 2011). "In a mouse Listeria monocytogenes infection model, it was observed that TLR2, responsible for the activation of MCs, plays a crucial role in regulating the synthesis of IL-6 and IL-13 during the innate immune response to this bacterium." (PMID 38638437, 2024).
liver cancer (4 papers, 2020 to 2024). An epithelial or non-epithelial malignant neoplasm that arises from the liver. "Third, the combined inhibition of CCL2 and IL13 profoundly impeded metastasis in our in vivo experimental model of liver cancer." (PMID 31933479, 2020). "Interestingly, compared with TPH1 + PMA + L02-SCR group, it is showed for the M2 polarization in TPH1 + PMA + L02-Sh group and TPH1 + PMA + IL-4 + IL-13 group, indicated decreased FPN1 promoted liver cancer cell M2 polarization." (PMID 34183746, 2021).
liver cirrhosis (4 papers, 2020 to 2024). "Although IL-13 is implicated in HSC activation, and IL-13 levels are up-regulated in patients with liver cirrhosis, the role of IL-13 in cholestatic liver injury has not been well defined." (PMID 36358290, 2022). "Lastly, a prospective clinical study was performed to measure CCL2 and IL13 in human patients with HCC (n = 25) and in patients with cirrhosis of the liver (n = 10)." (PMID 31933479, 2020).
lymph node metastasis (4 papers, 2018 to 2022). "Fold-change in IL13 expression was significantly lower in CRC patients with lymph node metastasis and inversely related to the TNM stage." (PMID 32512917, 2020). "In addition, IL-13 protein concentration was significantly lower in GC patients with lymph node metastasis when evaluated either in tumor (5.5 vs. 11.4, p = 0.008) or non-cancerous adjacent tissue (3.9 vs. 5.8, p = 0.039)." (PMID 32512917, 2020). "Moreover, IL-13 has been reported to promote proliferation of cancer cells and be related to lymph node metastasis in some malignancies." (PMID 30643796, 2018). "Elevated systemic IL-13 reflected the disease advancement in ESCC, particularly the presence of lymph node metastasis and the depth of tumor invasion, and tended to correlate positively with cancer stage and tumor grade in CRC." (PMID 32512917, 2020).
meningitis (4 papers, 2019 to 2025). A disorder characterized by acute inflammation of the meninges of the brain and/or spinal cord. "As expected, in the PFC, we observed increased levels of pro-inflammatory cytokines such as IL1-α, IL1-β, IL-6, IL-17, TNF-α, and INF-γ (P < 0.05) and decreased levels of IL-7, IL-10, and IL-13 (P < 0.05) in the 24-h meningitis group." (PMID 31901235, 2020).
metastatic disease (4 papers, 2015 to 2024). "A tendency for an increased concentration of IL-4, IL-10 and IL-13 in blood plasma of patients with metastatic disease was evident." (PMID 39456247, 2024). "IL-13 and IL-17 expression are associated with the promotion of metastatic disease in BCs, including those that are negative for estrogen receptor expression." (PMID 27169467, 2016). "We found that the expression of M2-specific cytokines such as interleukin (IL)-13, IL-10, and transforming growth factor-β (TGF-β) was markedly increased in hepatic metastatic tumors of ICAM-1−/− mice compared with that in WT mice." (PMID 26068788, 2015).
Myalgia (4 papers, 2017 to 2025). "The first study reported elevated masseter muscle levels of IL-6, IL-7, IL-8, and IL-13 in patients with TMD myalgia compared to a control group." (PMID 40142185, 2025). "Microdialysis revealed that the levels of IL-6, IL-7, IL-8 and IL-13 were higher in patients with TMD-related myalgia than controls." (PMID 37509035, 2023). "This study showed that the muscle levels of IL-6, IL-7, IL-8 and IL-13 were increased in patients with TMD myalgia and increased further in response to experimental tooth-clenching, as did jaw-muscle pain and fatigue." (PMID 28243900, 2017). "In conclusion, the masseter levels of IL-6, IL-7, IL-8 and IL-13 were elevated in patients with TMD myalgia and increased in response to tooth-clenching." (PMID 28243900, 2017). "Tooth-clenching increased IL-6, IL-7, IL-8, TNF and IL-13 in TMD myalgia patients and IL-6 and IL-8 in controls, in line with previous studies." (PMID 28243900, 2017). "G-CSF predicted fever, and IL-13 and IP-10 and IL-13 and IP-10 also predicted myalgia." (PMID 29774022, 2018). "The main findings were that the masseter levels of IL-6, IL-7, IL-8 and IL-13 were higher in TMD myalgia patients than controls and that repetitive tooth-clenching increased the levels of IL-6 and IL-8 in both groups, while IL-7, IL-13 and TNF increased only in patients." (PMID 28243900, 2017). "This is the first study to show elevated muscle levels of the pro-inflammatory cytokines IL-6 and IL-8 and the anti-inflammatory cytokines IL-7 and IL-13 in painful jaw muscles of patients with TMD myalgia which supports the hypothesis that patients with TMD myalgia have higher levels of cytokines." (PMID 28243900, 2017). "Interleukin 6 (IL-6) and interleukin 8 (IL-8) levels increased in response to tooth clenching in both groups, while interleukin 7 (IL-7), interleukin 13 (IL-13) and tumor necrosis factor (TNF) rose only in patients with TMD-related myalgia." (PMID 37509035, 2023).
Myocardial fibrosis (4 papers, 2021 to 2025). "Higher calibrated IB, representing heavier myocardial fibrosis, were positively associated with increased serum levels of IL‐13, in company with LV enlargement in DCM." (PMID 33943014, 2021). "Integrated backscatter (IB), a method of quantitative echocardiographic techniques was further used to assess the correlation between IL‐13 and myocardial fibrosis in DCM." (PMID 33943014, 2021).
non-small cell lung carcinoma (4 papers, 2013 to 2024). A group of at least three distinct histological types of lung cancer, including non-small cell squamous cell carcinoma, adenocarcinoma, and large cell carcinoma. "In non-small cell lung cancer (NSCLC), the expression levels of IL-13 have been found to be increased in all histological subtypes, with particularly elevated expression in squamous cell carcinoma (SCC) compared to large cell carcinoma (LCC)." (PMID 39267832, 2024). "Similarly, S100A9(+) inflammatory monocytes in patients with non-small cell lung cancer (NSCLC) are shown to suppress T-cells by production of arginase, iNOS, and the IL-13/IL-4Rα axis." (PMID 33919732, 2021). "Non-small cell lung cancer (NSCLC) biopsy specimens have high intratumoral concentrations of CXCR2 ligands (CXCL1, CXCL5, and CXCL8) and type 2 cytokines interleukin-4 (IL-4), IL-5, IL-10, and IL-13." (PMID 23665907, 2013).
parasite (4 papers, 2012 to 2023). "Indeed, in type-2-skewed responses, such as some parasite infections in the gut, IL-25 clearly drives the inflammation upstream of IL-4, IL-5, and IL-13 and therefore acts as a pro-inflammatory cytokine." (PMID 22539101, 2012).
pneumonitis (4 papers, 2010 to 2023). An inflammatory process affecting the lung parenchyma. "Pneumonitis risk was also modulated by polymorphisms in anti-inflammatory genes, including genetic variation in IL13. rs20541 and rs180925 each resulted in increased risk (HR:2.95, 95% CI:1.14–7.63 and HR:3.23, 95% CI:1.03–10.18, respectively)." (PMID 20811626, 2010). "IL13 polymorphisms had a similar effect on pneumonitis risk." (PMID 20811626, 2010).
polyposis (4 papers, 2011 to 2022). "It is quite likely that, in the APC Min/+ model of polyposis, IL-33 promotes polyposis formation via Th2 cytokines IL-4 and IL-13 as well as inflammatory cytokine IL-6, which facilitate mast cell function." (PMID 29499051, 2018). "In line, elevated protein levels of IL13 were shown previously in a subgroup of CRS patients with polyposis, and IL13 is spontaneously released from NP tissue." (PMID 21984922, 2011).
psychosis (4 papers, 2019 to 2026). "The main inflammatory factors associated with clinical outcome in psychosis were IL-15, IL-13, IL-16, and IL-8, which may be associated with poor clinical outcome." (PMID 37270510, 2023). "The main inflammatory markers associated with clinical outcome in psychosis were IL-15, IL-13, IL-16, and IL-8, which may be associated with poor clinical outcome." (PMID 35273531, 2022). "Increased IL-13 levels in converters highlight potential involvement of Th2-related pathways during transition to psychosis." (PMID 41958296, 2026). "Interestingly, other studies have reported that IL-13 may be involved in the improvement of psychopathology and symptomatologies in SCZ, suggesting that an anti-inflammatory response as mediated by the type-2 T helper cell pathway may contribute to a treatment-induced recovery in psychosis." (PMID 35273531, 2022).
renal cell carcinoma (4 papers, 2021 to 2025). "IL13 contributes to the oncogenic effects of renal cell carcinoma and chronic lymphocytic leukemia." (PMID 37534250, 2023). "In the model of BALB/c mice with renal cell carcinoma (RCC), circulating levels of M2-like markers and pro-angiogenic cytokines, including IL-4, IL-10, IL-13, and VEGF-A, were reduced in endostatin-treated animals in comparison with non-treated control." (PMID 34209679, 2021).
respiratory syncytial virus infection (4 papers, 2016 to 2024). "Activated lung ILC2s produce large quantities of IL-5 and IL-13 that contribute to eosinophilic inflammation and mucus production following respiratory syncytial virus infection (RSV)." (PMID 38827738, 2024). "During respiratory syncytial virus infection, elevated IL-13 induces and sustains long-term airway hyperreactivity and mucus production." (PMID 38508309, 2024). "Furthermore, IL-13 has been shown to significantly modulate respiratory syncytial virus infection, including decreasing the viral titers, inhibiting the lung IFN-γ production, and reducing weight loss, as well as affecting viral entry, replication, and cell-to-cell transmission." (PMID 38508309, 2024).
sensitization (4 papers, 2013 to 2021). "Skin sensitization is primary associated with induction of Th1 cells, promoting a cytotoxic CD8+ T-cell response and secretion of IL-2 and interferon (IFN)-γ, while respiratory sensitization generally involve CD4+ Th2 cells and are characterized by high levels of IL-4, IL-10 and IL-13." (PMID 25760038, 2015).